TCL1A (TCL1 family AKT coactivator A)
Diseases named in the same sentence as TCL1A in open-access papers (continued):
Sharing a sentence is not in itself a finding about the gene and the disease.
hepatocellular carcinoma (1 paper, 2021). A malignant tumor that arises from hepatocytes. "In hepatocellular carcinoma (HCC), high TCL1A levels in patients under sorafenib treatment correlate with an inferior overall and progression-free survival." (PMID 34771618, 2021).
liposarcoma (1 paper, 2017). A usually painless malignant tumor that arises from adipose tissue.
marginal zone lymphoma (1 paper, 2021). A usually indolent mature B-cell lymphoma, arising from the marginal zone of lymphoid tissues. "Hodgkin lymphoma (HL), and post-GC tumors such as splenic- and mucosa-associated lymphoid tissue (MALT) types of marginal zone lymphoma (MZL), as well as multiple myeloma (MM), are all consistently negative for TCL1A." (PMID 34771618, 2021).
melanoma (1 paper, 2022). A malignant, usually aggressive tumor composed of atypical, neoplastic melanocytes. "Lastly, we examined associations of IRF4 and TCL1A genes with irAEs development in patients with melanoma receiving ICI treatment." (PMID 36505471, 2022). "Associations of IRF4 and TCL1A expression with irAEs development were verified in the melanoma cohort receiving immune checkpoint inhibitors." (PMID 36505471, 2022).
myeloid malignancies (1 paper, 2024). "Interestingly, TCL1A is located on chromosome 14q32, which has been associated with an inherited predisposition to the development of myeloid malignancies." (PMID 38225345, 2024).
ovarian carcinoma (1 paper, 2023). A malignant neoplasm originating from the surface ovarian epithelium. "Thus, as previously noted, in case #25, OGM detailed the inversion of the long arm of chromosome 14 and showed that the breakpoints are located next to the BRMS1L gene at 14q32.13, a gene involved in breast and ovarian cancer, and next to the TCL1A locus at 14q13.2." (PMID 37046792, 2023).
primary effusion lymphoma (1 paper, 2021). A large B-cell lymphoma located in the body cavities, characterized by pleural, peritoneal, and pericardial fluid lymphomatous effusions and that is always associated with human herpes virus-8 (HHV-8). "This could explain why post-GC derived, TCL1A-negative primary effusion lymphomas (PEL) did not upregulate TCL1A upon EBV infection, whereas expression of TCL1A in BL and DLBCL lines was modulated by EBV." (PMID 34771618, 2021).
respiratory failure (1 paper, 2017). The significant impairment of gas exchange within the lungs resulting in hypoxia, hypercarbia, or both, to the extent that organ tissue perfusion is severely compromised. "Given the relationship between POU2AF1, TCL1A, and BLK expression and the development of BOS, we investigated the expression of these three genes in public data sets from blood of patients with other causes of respiratory failure." (PMID 29375549, 2017).
thymoma (1 paper, 2022). A neoplasm arising from the epithelial cells of the thymus. "We also observed that a pre-GC B cell population (STMN1, TCL1A) was preferentially enriched in thymoma." (PMID 35869073, 2022).
tumor (21 papers, 2009 to 2025). "The highly enriched TCL1A+ B cell population was found to be associated with a thermal TME with anti-tumor effects." (PMID 37791059, 2023). "To investigate the association between TCL1A+ B cells and tumor environment in the TCGA-TNBC cohort, which is a subset of the TCGA-BRCA cohort, we estimated the abundance of TCL1A+ B cells in each patient through the GSVA score of the gene signature." (PMID 37791059, 2023). "In T-PLL and CLL patients, the expression of tumor-associated TCL1A mRNA and protein shows considerable inter-patient variability." (PMID 34771618, 2021). "It was also implicated that TCL1A, together with consensus transcriptional regulators of tumor stem cells (e.g., OCT3/4, SOX2), promotes the transformation of Barrett’s esophagus to adenocarcinoma, with an increased expression in Barret’s over normal (negative) esophageal mucosa." (PMID 34771618, 2021). "Additionally, since TLS formation is closely associated with tumor immunotherapy efficacy, the expression level of TCL1A could serve as a basis for evaluating the efficacy of immunotherapy in OSCC patients." (PMID 38764038, 2024). "Other pathways, such as Ras (RAF1, RALBP1, RASSF1), TGF-β (CREB3L2/3, CREB5, TCL1A), Rap1, Hippo, and axonal guidance, further facilitate tumour migration and spread." (PMID 41007296, 2025). "Taken together, our results described that the TME of the high abundance TCL1A+ B cells’ patients is related to hot-tumor with an anti-tumor response." (PMID 37791059, 2023). "In CRC, high TCL1A correlates with tumor differentiation and clinical stage and is an independent factor for CRC-specific and disease-free survival." (PMID 34771618, 2021). "In Eμ-TCL1A mice, TCL1A overexpression led to upregulated ATM, a protein known as a tumor suppressor, and downregulated TCL1A in the DNA damage repair process in B cells undergoing GC transformation." (PMID 34206047, 2021). "Understanding how TCL1A is deregulated and how this can lead to tumor initiation and sustenance can help in future approaches to interfere in its oncogenic actions." (PMID 34771618, 2021). "Using a double transgenic mouse model overexpressing PTPROt and TCL1A, the same team that discovered TCL1A repression of PTPROt highlighted that PTPROt overexpression had a tumor suppressor effect in vivo, which had been previously identified in other studies." (PMID 34206047, 2021). "As high TCL1A expression correlates with an inferior clinical outcome, an effect of TCL1A on tumor sustenance is likely, and its impact on several different oncogenic pathways makes it an appealing target." (PMID 34771618, 2021). "Five cell types, TIMP1+M3, S100A8+N3, TUBB+Mcyl, LAMP3+DC3, and TCL1A+pDC, all of which were enriched in MSC2, were positively associated with tumor progression (FDR < 0.05)." (PMID 34659209, 2021). "Taken together, our data indicate that HSP90A leads to activation of AKT signaling through TCL1A stabilization, and thus contributes to multi-modal resistance of tumor cells." (PMID 31992715, 2020). "TCL1A+ B cells were distributed throughout the stroma, although they were also organized in B cell structures located adjacent to tumor epithelial fields." (PMID 26299617, 2015). "A low ratio of TCL1A/CD20 expression was significantly correlated with poor disease-specific survival, indicating that high TCL1A expression relative to the expression of the B cell marker CD20 in total tumor samples is correlated with improved survival." (PMID 26299617, 2015). "Therefore, the combination of nanomaterials targeting tumor-infiltrating B cells with estradiol is expected to induce antitumor effects in OSCC by regulating the expression of TCL1A in B cells." (PMID 38764038, 2024).
tumor (continued). "Subsequently, the gene signature of TCL1A+ B cells based on differential expression genes of TCL1A+ B cells versus other immune cells was used to explore the correlation with tumor microenvironment (TME) and construct a prognostic signature using a non-parametric and unsupervised method." (PMID 37791059, 2023). "In addition, we have also found that NANOG confers multi-aggressive phenotypes to tumor cells through transcriptional induction of TCL1A and subsequent activation of the AKT-signaling pathway." (PMID 31992715, 2020). "Furthermore, we demonstrate that HSP90A potentiates AKT activation through TCL1A-stabilization, thereby contributing to the multi-aggressive properties in NANOGhigh tumor cells." (PMID 31992715, 2020). "For example, AKT phosphorylation or inactivation kinetics do not consistently relate to TCL1A expression in both transgenic mice and patient–derived neoplasia, and AKT activation alone does not necessarily cause tumours in B cells." (PMID 19668332, 2009). "However, the anti-tumor role of TCL1A has also been reported recently." (PMID 37234171, 2023). "Interestingly, examination by four hot-tumor gene signatures showed that tumors with a high abundance of TCL1A+ B cells showed hot-tumor characterization, indicating that an immune checkpoint inhibitors-based therapy strategy might be helpful in such patients." (PMID 37791059, 2023). "Given TCL1A’s important role in tumor initiation, progression, and maintenance, investigating the modes of its oncogenic function and dysregulation can help to better understand the pathogenesis of these neoplasms and to contribute to the identification of possible new treatment targets." (PMID 34771618, 2021). "With multiple analysis strategies, we found that TCL1A+ B cells are positively correlated with several T cells, for example, activated CD8 T cells, which have been proven to support anti-tumor immune response." (PMID 37791059, 2023). "The results showed that TCL1A+ B cells from SD patients are more likely to be enriched in hypoxia, NFAT, and TNF-alpha pathways, correlated with tumor invasion and metastasis, indicating a pro-tumoral environment." (PMID 37791059, 2023). "Consistent with all above the results, immune-related genes were highly expressed in hot tumor, for instance, CXCL9, TCL1A, CCL19, CXCL13, MS4A1, and C4orf7." (PMID 33816503, 2021). "When the same analyses were done using PEA Oncology II profiling data, 10 proteins correlated to tumor stage (P < 0.05), for example, CD160, TNFRSF4/OX40L, XPNPEP2, SPARC, MAD homolog 5/SMAD5, CPE, hK8/KLK8, WIF‐1, TCL1A, and MIC‐A/B." (PMID 33768639, 2021). "In CLL and T-PLL, higher TCL1A levels correlate with more aggressive disease features, such as higher white blood cell (WBC) counts and faster tumor cell doubling, as well as a shorter overall/progression-free survival." (PMID 34771618, 2021). "A high TCL1A/CD20 (B cell) ratio, determined in total tumor samples from a separate patient cohort using qRT-PCR (n = 52), was also correlated with improved survival (p = 0.027)." (PMID 26299617, 2015). "Analysis of B- and plasma cells (26,156 cells) showed that germinal centre (GC) B-cells (RGS13+, NEIL1+), cycling B-cells (UBE2C+, TYMS+) and naïve B-cells (TCL1A+, IL4R+) were all enriched in HPV+ve tumours compared to HPV-ve tumours, while switched B-cell subsets were found in both." (PMID 39757146, 2025). "Thus, our results demonstrate that TCL1A is a client protein of HSP90A, and that HSP90A’s direct binding leads to it stabilization, thereby contributing to AKT activation in NANOGhigh tumor cells." (PMID 31992715, 2020). "Conversely, in OSCC, TCL1A is predominantly expressed in B cells rather than in tumor cells and may enhance the immune response against OSCC by augmenting the proliferation and antigen-presenting ability of B cells." (PMID 38764038, 2024).
tumor (continued). "Notably, emerging evidence indicates that TCL1A overexpression serves as a negative prognostic indicator not only in B-cell malignancies but also in various solid tumors, where it promotes tumor progression through modulating immune microenvironment and enhancing cell survival pathways." (PMID 41200167, 2025). "TCL1A was upregulated in a majority of PTCLs, whereas TCL1B was not significantly increased in any of the tested tumor subtypes." (PMID 38464090, 2024).
cancer (10 papers, 2009 to 2024). A tumor composed of atypical neoplastic, often pleomorphic cells that invade other tissues. "In agreement with other cancers, our study also showed that TCL1A was a protective risk for the survival of RC patients (HR = 0.530) and positively associated with the abundance of B cells." (PMID 33833937, 2021). "TCL1A is crucial for cancer development by expressing in a subpopulation of immune B cells (CD3-/CD19+/CD10+/CD34-)." (PMID 33833937, 2021). "The reactivation of this embryonic expression pattern also represents a plausible explanation for high TCL1A levels in solid tumors, especially in cancers harboring a cancer stem cell population." (PMID 34771618, 2021). "Inhibition of HSP90A with AUY922 robustly dampened AKT phosphorylation level and expression of the effectors in NANOG signaling, such as MCL-1, Cyclin A, and TCL1A across all tested cancer cells." (PMID 31992715, 2020). "As B cell expressed TCL1A was the most prominent marker correlated with patient survival, perhaps we should broaden our T cells biased view to include B cells in cancer immunology." (PMID 26299617, 2015). "Thus our data suggest an additional route by which TCL1A might cause cancer." (PMID 19668332, 2009). "TCL1A is an oncogene that has been shown to enhance cancer progression via its role in cell survival pathways, and it is commonly over-expressed in aggressive subtypes of many cancers." (PMID 30042829, 2018).
hematological malignancies (3 papers, 2021 to 2024). "Furthermore, deregulation of predominantly autosomal genes was observed, including TCL1A overexpression in 45, X B-lymphocytes and other known genes associated with hematological malignancies." (PMID 36460769, 2022). "Another protein that can affect DNA methylation is the TCL1A protein, which inhibits DNMTs biochemically and affects global methylation in a mouse model of hematological malignancies." (PMID 39189258, 2024). "Another protein that can affect DNA methylation is the TCL1A protein, which was shown to inhibit DNA methyltransferases biochemically and affect global methylation in a mouse model of hematological malignancies." (PMID 39189258, 2024).
hematological neoplasms (1 paper, 2021). "T-cell leukemia/lymphoma 1A (TCL1A) was first described as a proto-oncogene in hematological neoplasms between 1989 and 1994." (PMID 34771618, 2021).
infection (1 paper, 2021). The state of being infected such as from the introduction of a foreign agent such as serum, vaccine, antigenic substance or organism. "Accordingly, most cell lines that showed an upregulation of TCL1A after infection in vitro expressed a type I latency." (PMID 34771618, 2021). "In support of positive regulation of TCL1A expression via EBV, infection of BL cell lines and a MM cell line by EBV induced upregulation of their TCL1A expression." (PMID 34771618, 2021).
TCL1A also shares sentences with these, for which no sentence is quoted: mantle cell lymphoma (3 papers); autoimmune disease (2); hematologic cancer (2); acute lymphoblastic leukemia (1); colitis (1); diabetes (1); diffuse large B-cell lymphoma (1); follicular lymphoma (1); hairy cell leukemia (1); heart failure (1); lymphocytic leukemia (1); lymphoplasmacytic lymphoma (1); nasopharyngeal carcinoma (1); non-Hodgkin lymphoma (1); Primary Sjögren’s syndrome (1); psoriasis (1); splenic marginal zone lymphoma (1); Splenomegaly (1); triple-negative breast carcinoma (1).